ETV6 (ETS variant transcription factor 6)
Diseases named in the same sentence as ETV6 in open-access papers (continued):
Sharing a sentence is not in itself a finding about the gene and the disease.
cancer (76 papers, 2008 to 2026). A tumor composed of atypical neoplastic, often pleomorphic cells that invade other tissues. "Additional investigation into how the presence of the ETV6/RUNX1 translocation impacts the adenoviruses ability to modulate cellular genes associated with cancer progression is of great interest." (PMID 41497616, 2025). "The gene fusion seen in nearly all of these types of cancer is ETS translocation variant 6 (ETV6)–NTRK3 fusion." (PMID 37212982, 2023). "In our case with the ETV6::SNCB rearrangement, we observed a similar loss of wild-type ETV6, which likely promotes cancer progression through a similar mechanism." (PMID 37251917, 2023). "The fusion variant of ETV6- NTRK3 was noted in 4 out of 17 ETV6 translocation-positive secretory carcinomas, which were defined by FISH assays." (PMID 31822803, 2020). "Published studies show that gene ETV6, identified as associated with eight and seven cancer types by A1 and A2, respectively, is involved in the transcriptional dysregulation of cancer pathways." (PMID 31405076, 2019). "Recent studies identified germline ETV6 variations associated with marked familial clustering of hematologic malignancies, pointing to this gene as a potentially important genetic determinant for ALL susceptibility." (PMID 26522332, 2015). "In addition, we detected variants in several known cancer predisposition genes (eg, ETV6, RUNX1, ANKRD26, and IKZF1), highlighting the importance of long-term surveillance and genetic counseling in IPDs with potential malignant transformation risk." (PMID 40488176, 2025). "ETV6 is originally involvement in chromosomal translocation linked with hematologic and various cancers, a lot of chromosomal translocation oncogenes have been identified, as a transcriptional repressor, ETV6 is biologically important in embryonic development and haematopoietic regulation." (PMID 38683131, 2024). "ETV6 is a master TF in normal development and is recurrently mutated in cancer." (PMID 36658220, 2023). "The high multi‐cancer diagnostic value of small eccDNAs originated from ALK&ETV6 could be extrapolated from tissues (AUC = 0.804) to plasma and showed high positive predictive value (100%) and negative predictive value (82.35%) in a validation cohort." (PMID 37649244, 2023). "Interestingly, negative regulators of enhancer-associated genes including the TFs CEBPA, IRF8, IRF1 and ETV6, can suppress cancer cell growths." (PMID 31665430, 2020). "Indeed, many of the TFs and chromatin modifiers identified amongst Etv6’s 540 direct target genes have previously been directly or indirectly implicated in the regulation of VegfA in endothelial and cancer cells." (PMID 30842454, 2019). "(J) Representative persistent DMR in the enhancer of a cancer-associated gene (Etv6)." (PMID 30963999, 2019). "The impact on cancer causation of a category of "unproductive" translocations, such as ETV6 gene fusions, remains unclear." (PMID 18947387, 2008). "Indeed, breaks at cRSSs in cancer driver genes were found to be a predominant cause for cancer progression in ETV6/RUNX1 ALL, and our LAM-HTGTS experiments suggest the ESC could play a role in causing some of these breaks." (PMID 31333681, 2019). "The AML had overall gained 4 mutations in cancer genes: ETV1 (p.R405H, VAF 30.4%), KRAS (p.G12A, VAF 27.9%), PARP1 (c.2277 + 1G > C, VAF 7.5%), and ETV6 (p.I358M, VAF 5.3%)." (PMID 38012682, 2023). "As in adults, more aggressive cancer behavior is expected in cases harboring p.V600E or other BRAF point mutations or BRAF-like fusions (e.g., RET/PTC1, NTRK3/ETV6, ALK rearrangements), although these correlations remain unconfirmed in children." (PMID 37046700, 2023). "Collectively, these studies demonstrated that inhibiting PNT domain polymerization is indeed a viable therapeutic strategy against ETV6-driven cancers." (PMID 33450226, 2021). "It has been pointed out that ETV6 is a highly promiscuous gene since it has been reported as having 30 ETV6 partner genes in cancer." (PMID 31096545, 2019).
cancer (continued). "In an analysis of 24 breast tumours, rearrangements were found in known cancer genes including BRAF, PAX3, PAX5, NSD1, PBX1, MSI2 and ETV6, each of which is a partner in a fusion gene in several other human cancers." (PMID 24792170, 2014). "Furthermore, we leveraged the noncoding genome and methylome to identify inherited epimutations in genes including ASXL1, ETV6, and LEF1 that confer increased cancer risk." (PMID 37377903, 2023). "Furthermore, we evaluated the noncoding genome and methylome and identified inherited epimutations in genes including ASXL1, ETV6, and LEF1 that confer increased cancer risk." (PMID 37377903, 2023). "Indeed, great multi‐cancer diagnostic value in tissues was observed in small eccDNAs originated from some specific genes, especially the combination of PLD1 and ATF6, or ETV6 and ALK." (PMID 37649244, 2023). "Importantly, the combination of small eccDNAs originated from ETV6 (cut‐off point: 0.000019) and ALK (cut‐off point: 0.000022) showed great multi‐cancer diagnostic value in tissues." (PMID 37649244, 2023). "In a similar study of NTRK fusions in cancer patients, those harboring fusions with any of the 3 most frequent partners ETV6, TPM3, and LMNA comprised 22.3% (198/889) of all NTRK‐positive cases, a percentage closer to our observation with MET (13/122 patients, 10.7%)." (PMID 37326363, 2023). "Indeed, functional germline mutations of some cancer-related genes have been found in familial ALL (e.g., PAX5 and ETV6) or enriched in sporadic cases (e.g., ETV6 and CDKN2A), accounting for a small proportion of ALL patients." (PMID 32595701, 2020). "ETV6 affects cancer cells’ malignancy by interrupting cellular F-actin polymerization." (PMID 32326970, 2020). "We observed no pathogenic germline ETV6 mutations in children with cancers other than ALL in the PCGP." (PMID 26102509, 2015). "ERG, ETV1, ETV4, ETV6, FLI1, and FEV, are implicated in the pathogenesis of several cancers." (PMID 21789226, 2011). "Moreover, our aCGH analyses of the same series showed that some cases without mutation in the studied genes do have deletions of other cancer genes (for example CDKN1B, ETV6 and UTX are deleted in HD-0205)." (PMID 20678218, 2010). "As ETV6 is a ubiquitously expressed transcriptional repressor, which was shown to form fusion genes with oncogenic consequences in a number of hematological malignancies and solid tumors, it would be crucial to determine whether BCL2L14-ETV6 fusion occurs in other types of cancer." (PMID 37031274, 2023). "CDKN2A, IKZF1, ETV6, RUNX1, and FLT3 were the top genes mutated in leukemias, while somatic alterations in ALK, NF1, and PTEN primarily occurred in solid tumors, suggesting that the driver alterations are either common to cancer (e.g., cell cycle) or specific to pediatric cancer histotype." (PMID 36845394, 2023). "In addition, ETV6 is frequently involved in chromosomal translocations in different cancers." (PMID 36292767, 2022). "However, in our series, 1 case of SC with an intact ETV6 gene had the PRSS1 mutation, suggesting that other mechanisms may be involved in the PRSS1 mutation of zymogen granule-poor cancers." (PMID 31822803, 2020). "Taken together, these findings reveal that the ETV6-miR-429-CRKL regulatory circuitry plays a crucial role in glucose metabolic reprogramming in HCC, offering novel insight and a potential target for cancer therapy." (PMID 41631407, 2026). "More strikingly, the combination of ETV6 and ALK can also be extrapolated to multi‐cancer diagnostics in plasma and was validated in an independent cohort." (PMID 37649244, 2023).
cancer (continued). "Eight of the cis-CSCE lie in cancer genes on our Tier 3 list, including ASXL1 (qCSCE = 1.04 × 10−2;rhoCSCE = −0.371) and ETV6 (qCSCE = 2.41 × 10−2; rhoCSCE = 0.386)." (PMID 37377903, 2023). "Some of the most prevalent included known pediatric cancer fusions RUNX1::RUNX1T1 (15% AML participants), KMT2A::MLLT3/MLLT10 (12% AML), TCF3::PBX1 (4.4% ALL), and ETV6::RUNX1 (2.4% ALL)." (PMID 37323575, 2023). "For the LUAD network, four TFs, ETV1, ETV4, ETV6, and ELK4, were involved in the pathway called “transcriptional mis-regulation in cancer”." (PMID 35524179, 2022). "ETV6 break FISH was positive and pan-cancer panel resulted in ETV6-NTRK3 fusion (split read: 339, spaning read: 40)." (PMID 32957984, 2020). "We found significant joint over expression of the JUN and FOS proto oncogenes in a cluster of cells for sample ETV6.RUNX1.2, suggesting deregulation in stress/cancer genes." (PMID 32415257, 2020). "It is worth noting that five of these genes (PIK3CA, HRAS, AKT1, ETV6, and KDM5C) are known to play important roles in cancer and are CGC genes (that is, experimentally validated cancer genes)." (PMID 25360158, 2014). "Four carcinomas harbored atypical ETV6 FISH patterns, of which 3 were found in non-parotid locations, and 2 cases presented as recurrent disease." (PMID 39101978, 2024). "Additionally, CNV analysis identified amplification of PNP, FCGR3A, and CFHR1 as well as deep deletion of ETV6, CFHR1, and RPS15 as the most frequently detected copy number altered PID-related genes across the four available pediatric cancer cohorts." (PMID 36497424, 2022). "Genetic profiling showed that the secretory carcinomas with intact ETV6 genes had genetic alterations that were not significantly different from those of the secretory carcinomas with ETV6 gene translocation." (PMID 31822803, 2020). "An intestinal immune network for IgA production might provide new markers in enteric DLBCL, such as CCR10, TNFRSF13B, AICDA, and HLA-DOB, as well as genes involved in transcriptional misregulation in cancer (NFKBIZ, FUT8, LMO2, CCND2, BCL2A1, ETV6, and CDK14)." (PMID 29992138, 2018). "To date, it is not known whether the ETV6 pathway contributes to non-leukemic cancer phenotypes." (PMID 26102509, 2015). "Furthermore, ETV6 is not regulated by EWS–FLI and does not exhibit a marked pattern of expression specific to this cancer type." (PMID 36658220, 2023).
hematological malignancies (34 papers, 2008 to 2025). "Acting in a dominant negative manner, ETV6 mutations have been reported in various hematological malignancies in the reproductive system, including B-ALL as the most common one in children, and other hematological malignancies such as T-ALL, MDS, and AML." (PMID 37767202, 2023). "ETV6::ABL1 gene fusion is a rare recurrent genomic rearrangement associated with hematologic malignancies, and frequently occurs with additional anomalies." (PMID 37895201, 2023). "Genetic alterations in the transcriptional repressor ETV6 are associated with hematological malignancies." (PMID 30341373, 2018). "With the recent reports connecting germline ETV6 mutations to a panel of familial hematological diseases and given the complexity of ETV6-mediated transcription, further characterization of ETV6 remains valuable." (PMID 30341373, 2018). "In recent years ETV6 was shown to be involved in a variety of translocations associated with hematological malignancies of both myeloid as well as lymphoid origin." (PMID 21401966, 2011). "However, ongoing research continues to investigate the pathogenic mechanisms of the ETV6 gene in hematological disorders." (PMID 40008001, 2025). "However, the well‐defined association of ETV6 germline mutations and hematologic malignancies, would entail a predisposition to malignancies in this family." (PMID 30950205, 2019). "The wide spectrum of hematological diseases associated with ETV6 alterations could be explained, at least partially, by the distinct ETV6 regulatory network of the cell originally affected by the mutation." (PMID 30341373, 2018). "Consistent with recent reports of recurring germline ETV6 mutations associated with familial thrombocytopenia and overrepresentation of hematologic malignancies, this p.R359X variant in ETV6 is likely to be responsible for the ALL predisposition in this family." (PMID 26522332, 2015). "The ETV6 gene has been identified to play a role in the development of multiple hematologic malignancies." (PMID 41123786, 2025). "ETV6::JAK2 (TEL::JAK2) is found in various hematologic malignancies and results in constitutive kinase activity." (PMID 40140631, 2025). "Chromosomal translocations generate the aberrant fusion TKs, such as BCR-ABL1, Ets variant gene 6-ABL1 [TEL(ETV6)/ABL1], TEL(ETV6)/JAK2, and TEL-platelet-derived growth factor beta receptor [TEL(ETV6)/PDGFβR], which induce hematologic malignancies." (PMID 27233483, 2016). "One example of an Ets factor that is involved in several different types of hematological malignancies is Tel (ETV6)." (PMID 20454645, 2010). "Notably, heterozygotes for germline P/LP variants in GATA2, ETV6, and RUNX1 (both cohorts), and DDX41 (UKBB only) have significantly increased risk for developing hematological malignancies." (PMID 39501104, 2025). "ETV6 and CDKN1B, linked to cell cycle regulation and hematologic disorders, may also contribute to additional systemic manifestations." (PMID 40243517, 2025). "ETV6::ABL1 rearranged neoplasms are rare hematological diseases." (PMID 38203288, 2023). "Mice expressing the ETV6/RUNX1 fusion and the SB transposase variant HSB5 from the endogenous Etv6 locus had a background of long latency hematologic malignancies similar to wild type controls i.e. the fusion itself caused only slightly higher rates of lymphomagenesis." (PMID 34484175, 2021). "Interestingly, the 12p13.2 breakpoint fell into the ETV6 gene, which results partially deleted; this type of deletion has been detected in a broad spectrum of hematological malignancies, frequently with monosomy 7, such as in our case." (PMID 29108298, 2017). "The ETV6 gene (ETS variant gene 6) on the short arm of chromosome 12 encodes a transcriptional repressor of the ETS transcription factor family which is fundamental in adult hematopoiesis and plays a versatile role in hematological malignancies." (PMID 21401966, 2011).
hematological malignancies (continued). "Because ETV6 has been shown to be important for yolk sac angiogenesis, its upregulation in several hematological malignancies also suggests that it may likely play an important role in regulating angiogenic factors in hematological malignancies." (PMID 20454645, 2010). "Multiple chromosomal rearrangements involving ETV6 (such as ETV6::RUNX1, ETV6::ABL1, ETV6::NTRK3, and ETV6::ACSL6) have been demonstrated to play a crucial role in the development of several hematologic diseases such as AML, as well as in their diagnosis and prognosis." (PMID 39723366, 2024).
hematologic neoplasms (5 papers, 2018 to 2025). "We observed that Nfkb1 exhibited higher transcriptional activity in Nrp1 + DT cells, whereas Etv6, a transcription factor known mainly for its role in hematology and blood cancers, showed higher activity in Nrp1-DT cells." (PMID 38977708, 2024).
adenocarcinoma (3 papers, 2017 to 2025). A common cancer characterized by the presence of malignant glandular cells. "The diagnostic ETV6 alterations help identifying SC cases from adenocarcinomas, NOS." (PMID 28484662, 2017). "High-grade adenocarcinoma with similar morphology and an ETV6::NTRK3 fusion, arising in the parotid gland of a 22-year-old male patient, was reported recently." (PMID 37415052, 2023). "For the first time, we describe 2 cases of primary high-grade non-intestinal type adenocarcinomas of the nasal cavity, distinct from secretory carcinoma by morphology and immunoprofile, harboring the ETV6::NTRK3 fusion." (PMID 37415052, 2023).
hematopoietic neoplasm (3 papers, 2013 to 2025). "As one example, MPN18 harbored hematologic cancer-associated gene mutations in ASXL1, ETV6, and SRSF2 at baseline." (PMID 31911629, 2020).
infection (3 papers, 2015 to 2025). The state of being infected such as from the introduction of a foreign agent such as serum, vaccine, antigenic substance or organism. "Twenty-eight days into the infection, hexon, E2A and E3-gp19K mRNA levels were significantly reduced in cells expressing either ETV6/RUNX1 or RUNX1/MTG8RUNX1 compared to expression levels in empty vector containing cell." (PMID 41497616, 2025). "While the length of time required for loss of hexon mRNA varies between three replicate infections, expression was robustly reduced in RUNX1/MTG8 or ETV6/RUNX1-expressing B cells between 7 to 10 weeks post infection." (PMID 41497616, 2025). "The infection of primary blasts isolated from the bone marrow of pre-B ALL patients with a lentiviral vector expressing miR-181a increased the level of miR-181a by an average of 2.5-fold (range from 1.5- to 3-fold) in three ETV6/RUNX1-positive samples compared with the controls." (PMID 26580398, 2015). "Again, there was a considerable amount of heterogeneity in the copy number present during each infection but the fold change significantly increased 6-fold in ETV6/RUNX1-positive cells and 5-fold in RUNX1/MTG8-positive cells on average in each infection." (PMID 41497616, 2025). "For example, one infection contained 2.2 × a104 AdV genomes in ETV6/RUNX1-containing cells, 52 days post infection, as compared to 1.3 × 108 in empty vector containing cells at the same time." (PMID 41497616, 2025). "Our current data reveals that the presence of ETV6/RUNX1 does not inhibit subsequent infections with adenovirus and, in fact, may enhance the level of virus present during acute infection." (PMID 41497616, 2025). "Here we show that the common leukemic fusion proteins, ETV6/RUNX1 or RUNX1/MTG8, reduce adenovirus persistence in a B-lymphocyte line but do not dampen the initial acute infection phase." (PMID 41497616, 2025). "The common RUNX1 leukemic fusion genes ETV6/RUNX1 and RUNX1/MTG8 had no impact on viral gene expression during the acute phase but accelerated the decrease in viral gene expression and viral DNA replication during the persistent phase of infection." (PMID 41497616, 2025).
ETV6 also shares sentences with these, for which no sentence is quoted: myeloproliferative disorder (8 papers); chronic myelomonocytic leukemia (6); congenital mesoblastic nephroma (5); chronic lymphocytic leukemia (4); salivary duct carcinoma (4); bone marrow failure (3); bone marrow failure syndrome (3); melanoma (3); T-lymphoblastic lymphoma (3); acute promyelocytic leukemia (2); anemia (2); Burkitt lymphoma (2); diffuse large B-cell lymphoma (2); Fanconi anemia (2); inflammatory myofibroblastic tumor (2); lung carcinoma (2); multiple myeloma (2); myelofibrosis (2); Obesity (2); sinonasal carcinomas (2); T-cell acute lymphoblastic leukemia (2); acute monocytic leukemia (1); angiomatoid fibrous histiocytoma (1); apocrine carcinoma (1); atherosclerosis (1); basophilic leukemia (1); bone tumors (1); brain infarction (1); brain tumor (1); carcinoid (1).
A further 59 diseases each share a sentence with ETV6 in 1 paper.